EGFR (epidermal growth factor receptor)
Diseases named in the same sentence as EGFR in open-access papers (continued):
Sharing a sentence is not in itself a finding about the gene and the disease.
breast carcinoma (continued). "Drawing from the PPI and enhanced KEGG analyses, we hypothesize that the therapeutic efficacy of TSAC in breast cancer may be linked to its inhibitory effects on the EGFR/PI3K/Akt signaling pathways." (PMID 40864816, 2025). "Consequently, there is an urgent need to develop a non-invasive and efficient method for predicting the risk of EGFR mutations in patients with breast cancer before treatment." (PMID 41179692, 2025). "Prior studies have shown associations between EGFR mutations and poor breast cancer prognosis." (PMID 41162424, 2025). "Recent in vitro investigations have elucidated that CD147 facilitates the assembly of a multiprotein complex comprising CD147, CD44, and EGFR in lipid raft-associated microdomains of the cell membrane, thereby enhancing the invasion of breast cancer cells such as MDA-MB-231 and MCF-7." (PMID 41479915, 2025). "KEGG pathways revealed associations with the ErbB signaling pathway and breast cancer, while Wiki pathways highlighted connections with inflammation resolution pathways involving resolvins E1 and D1, as well as inflammation-related pathways involving COX2, EGFR, and the ErbB signaling pathway." (PMID 40731912, 2025). "Our data provides evidence that breast cancers with EGFR amplification and PI3K pathway activating mutations may be more likely to respond to therapies targeting these pathways." (PMID 40501689, 2025). "Taking into consideration the differential expression of certain ECM molecules and receptors in breast cancer cells, we further evaluated the relationship of ERs and the two RTKs, EGFR and IGF-IR, with critical matrix macromolecules implicated in breast cancer progression." (PMID 41228316, 2025). "The expression levels of EGFR show significant differences across various breast cancer subtypes, which may be closely associated with clinical prognosis." (PMID 40620253, 2025). "EGFR is a COSMIC21 consensus gene associated with breast cancer risk." (PMID 38684708, 2024). "YTHDF3 promotes the translation of m6A-modified mRNAs of breast cancer brain metastasis-associated genes (e.g., ST6GALNAC5, GJA1, and EGFR) by recruiting eIF3a and increasing the expression of the corresponding proteins, which ultimately affects the brain metastasis of breast cancer." (PMID 39440064, 2024). "Notably, ERBB2, also known as HER2, has been well-documented for its overexpression in breast cancer and is a validated therapeutic target, as is EGFR, which is implicated in various cancers including breast cancer." (PMID 38306344, 2024). "Interestingly, GEPs induced by different concentrations of ORes were significantly enriched in the PI3K-AKT signalling pathway downstream of EGFR, and activation of the EGFR/PI3K/AKT/GPX4 axis was associated with poor prognosis in breast cancer patients." (PMID 39881871, 2024). "EGFR is a receptor associated with proliferation, survival, and chemoresistance in breast cancer." (PMID 39698031, 2024). "In this regard, TCDD-induced EGFR expression changes in breast cancer cells were associated with downstream signaling activation and apoptosis inhibition, whereas this effect was reversed by an AhR antagonist, indicating a tumor-promoting effect of EGFR-mediated AhR signaling." (PMID 39211042, 2024). "As a proof-of-concept for how genetic methods may identify causal cancer genes we used this approach to highlight a causal role of EGFR in breast cancer risk." (PMID 38684708, 2024). "Indeed, given the wide array of disease targets, including targets such as EGFR and Src associated with breast cancer, it is evident that there is a compelling need to design multi-target molecules for treating complicated diseases." (PMID 38924082, 2024). "Potentially actionable molecular alterations include agnostic targets (NTRK1-2-3, RET fusions, BRAF V600E mutations, microsatellite instability, high tumor mutational burden), or tissue-specific targets, such as EGFR mutation in NSCLC or PIK3CA mutations in breast cancer." (PMID 39766151, 2024).
breast carcinoma (continued). "EGFR overexpression may be caused by estradiol, while activation of its derived signaling pathways amplifies the role of estradiol in breast cancer." (PMID 38465341, 2024). "Thus, it necessitates the design and generation of efficacious EGFR inhibitors to target the downstream signaling associated with the cellular proliferation and tumorigenesis of breast cancer." (PMID 38522013, 2024). "HER3 has been implicated in breast cancer resistance to multiple therapies, including antiestrogen therapies fulvestrant and tamoxifen, EGFR and HER2 small molecule inhibitors such as erlotinib and lapatinib, and HER2 directed antibodies such as Herceptin (trastuzumab) and Pertuzumab." (PMID 38951909, 2024). "EGFR has been linked to the pathogenesis and progression of human breast cancer." (PMID 38951817, 2024). "In contrast, in canine mammary tumors, an association between Cox-2 and EGFR was revealed." (PMID 38785565, 2024). "This could imply a disruption in signal transduction through integrin β1 associated with reduced ER and EGFR status in the studied breast cancer cells." (PMID 36982173, 2023). "Interestingly, PI4P5KIγ expression was linked to poor prognosis in breast cancer by regulating crucial steps in cancer metastasis, E-cadherin cell-cell contacts, and EGFR-stimulated cell migration." (PMID 37408244, 2023). "Therefore, DHA C22:6n-3 at high concentrations, by inhibiting EGFR activity, causes apoptosis of cancer cells, as demonstrated in breast cancer cells and pancreatic cancer cells." (PMID 37046844, 2023). "In addition, the HLA-DQA1 gene predicts hepatotoxicity risk in breast cancer treated with epidermal growth factor receptor (EGFR) inhibitors." (PMID 37434241, 2023). "Overexpression of EGFR is associated with poor outcomes in various malignancies, including breast cancer, and EGFR overexpression is more frequently found in triple-negative/basal-like breast cancer compared to other molecular subtypes." (PMID 37760847, 2023). "Correlation of EGFR mutation and Ki67 expression of breast cancer." (PMID 36313724, 2022). "These values are consistent with plasma versus tissue PPA estimates for FDA‐approved plasma CDx assays, such as Therascreen® PIK3CA RGQ PCR Kit [54.6%; breast cancer (alpelisib)] and cobas® EGFR Mutation Test v2 [≥58.7%; NSCLC (erlotinib, osimertinib, gefitinib)]." (PMID 35338679, 2022). "The effect of CD82 palmitoylation site mutation on the expression, location, and metabolism of EGFR and c-Met in breast cancer cells remains unclear so far." (PMID 35538033, 2022). "Notably, MGL S3, but not MGL tetani, caused ERK downregulation in neuroblastoma (SH-SY5Y) and breast cancer (SK-BR-3) cells, that represent cancer types that have a strong correlation between EGFR dependency and methionine metabolism genes expression." (PMID 36361596, 2022). "For instance, cross-linked function of Notch and EGFR (epidermal growth factor receptor) signaling is highly associated with occurrence of breast cancer which was reported when Notch1 overexpression promoted cell growth accompanied by upregulated EGFR expression levels." (PMID 36017236, 2022). "To overcome these challenges, we employed gold nanoparticles modified with trimethyl chitosan (TMC) as an effective delivery carrier to improve the stability and cellular uptake of siRNAs against epidermal growth factor receptor (EGFR) that is implicated in breast cancer." (PMID 35517864, 2022). "The over-expression of ESR-α and EGFR signaling pathways are associated with mammary carcinoma." (PMID 36107265, 2022). "Overexpression and activation of AKT and mTOR, as sub-pathways of EGFR, are directly linked to the development of breast cancer, and we demonstrated that n-10 fatty acids have an impact on these two signaling proteins, in connection with but also independently from EGFR." (PMID 35053341, 2022).
breast carcinoma (continued). "In particular, tamoxifen resistance is associated with enhanced glycolysis in ER-positive breast cancer cells through activation of EGFR/MAPK pathway, a pathway also responsible for ligand-independent Erα activation In the MPA-induced tumor model, the FGF-2/FGFR-2 axis drives HI growth." (PMID 35299741, 2022). "Correlation of EGFR mutation and PR status of breast cancer." (PMID 36313724, 2022). "In addition, activating PIK3CA mutations in basal-like breast cancer were found to induce paracrine activation of AREG/EGFR/ERK signaling." (PMID 34207383, 2021). "However, the overexpression of EGFR is observed in 15–30% of breast carcinomas and is associated with a large tumor size and poor clinical outcomes." (PMID 33572326, 2021). "Overexpression of EGFR has been associated with most cancer types, including breast cancer." (PMID 33925065, 2021). "However, studies show that EGF is likely to induce tumor cell invasion in breast cancer, where the overexpression of EGFR is connected with the loss of estrogen receptor and poor prognosis." (PMID 34277608, 2021). "Among 22 NSCLC patients, IHC of PD-L1 using the 22C3 antibody was possible in 19 patients except for 1 patient each where EBUS-TBNA was performed to differentiate between lung and breast cancer recurrence for staging purposes and to search for T790M mutation in EGFR-positive NSCLC, respectively." (PMID 33963234, 2021). "Resistance to ERBB2-targeted therapy including the use of trastuzumab, an anti-ERBB2 monoclonal antibody, and lapatinib, a small molecule kinase inhibitor of ERBB2 and EGFR, is associated with alternations of signal transduction pathways, apoptosis, and cell cycle control in breast cancer." (PMID 33801244, 2021). "Co-expression analysis and gain- or loss-of-function of PTK7 in TNBC cell lines revealed that PTK7 participates in EGFR/Akt signaling regulation and associated with extracellular matrix organization and migration genes in breast cancer, including COL1A1, FN1, WNT5B, MMP11, MMP14 and SDC1." (PMID 34367983, 2021). "In addition, the GPER-1/EGFR signaling axis mediates the expression of cell cycle regulatory genes in cancer-associated fibroblasts derived from breast cancer patients, favoring tumor progression." (PMID 33117280, 2020). "Furthermore, a previous study revealed that CDK4 and MDM2 mutations occurred in melanomas and liposarcoma, while ERBB2 mutations occurred in breast cancer, EGFR mutations occurred in astrocytoma, and MYCN mutations occurred in neuroblastoma." (PMID 32711494, 2020). "Since activating EGFR and Ras mutations are rare in breast cancer, activation of Ras proteins in TNBC may be dependent on mostly wild type oncogenic receptor tyrosine kinases via RasGEFs such as SOS1 and GRF2." (PMID 32298357, 2020). "Importantly, co-expression of GLI1 and two GLI1 targets, EGFR and Snail, are associated with worse outcome in breast cancer patients, further underscoring the clinical relevance of this pathway." (PMID 32391382, 2020). "The study, which included 311 early-stage breast cancer patients, investigated associations between preoperative serum levels of EGFR and EGFR ligands (epidermal growth factor, heparin-binding epidermal growth factor (HBEGF), amphiregulin, transforming growth factor-α and betacellulin) and survival." (PMID 33024132, 2020).
breast carcinoma (continued). "β1-integrin has been linked to the tumorigenic properties of EGFR in both lung and breast cancer and Rab13 may mediate this interaction, both intra- and extracellularly." (PMID 32978434, 2020). "The primary aim of the present study was to investigate whether preoperative serum levels of EGFR and EGFR ligands were associated with overall survival and invasive disease-free survival in early-stage breast cancer patients." (PMID 33024132, 2020). "Over expression of EGFR in most basal-like breast cancer suggests that basal-like tumors may be caused by excessive activation of the growth factor receptor pathway in a manner similar to Her-2+ breast cancer." (PMID 33552956, 2020). "Biomarkers used in clinical practice for treatment stratification are, e.g., the human epidermal growth factor receptor 2 (HER-2) status for breast cancer patients or presence of epidermal growth factor receptor (EGFR) mutation in non-small cell lung cancers (NSCLC)." (PMID 31312252, 2019). "Similarly, another important component of the miRNA biogenesis pathway, AGO2, has been found to be phosphorylated under hypoxic conditions by EGFR in breast cancer cells where it was shown to mediate EGFR-associated tumor cell invasiveness." (PMID 31906022, 2019). "The over‐expression of EGFR in breast cancer is associated with poor differentiation and prognosis." (PMID 31408580, 2019). "Moreover, diabetes mellitus (DM), especially type 2 diabetes, has been recently regarded as a risk factor in breast cancer, due to the fact that high blood–glucose levels can stimulate EGFR activation and then trigger the EGFR/Cdc42 positive loop." (PMID 30754684, 2019). "In particular, the association between TGF‐β and EGFR in breast cancer is poorly described." (PMID 29215776, 2018). "Combined, these data indicate that diagnostic or therapeutic chest radiation may predispose patients with decreased stromal PTEN expression to secondary breast cancer, and that prophylactic EGFR inhibition may reduce this risk." (PMID 30018330, 2018). "As a potential regulatory mechanism that promotes ER dependency for cell proliferation and survival in ER+ breast cancer cells, receptor tyrosine kinases (RTKs), such as EGFR and IGF1R, and their associated ligands, including IRS2, are putative targets of miR-7." (PMID 30214383, 2018). "Moreover, quantitative analysis suggested that Sp1 and Smad3 caused an additive effect on EGFR expression in breast cancer cells." (PMID 29215776, 2018). "Importantly, intracellular and nuclear EGFR is strongly correlated with poor therapeutic responses and metastatic progression in breast cancer, resulting in a 3.4 times greater mortality risk." (PMID 29464085, 2018). "Interestingly, EGFR T790M mutations have recently been observed in biopsies of completely untreated primary breast cancer, indicating immediate drug resistance against most of the available EGFR targeting drugs in subgroups of MBC patients." (PMID 27923036, 2017). "Breast cancer metastasis remains a major health problem associated with exceptionally poor patient survival, and many lines of evidence indicate EGFR has a pivotal role in increased cell motility, invasiveness, and progressive regional and distant metastasis of breast cancer." (PMID 28947780, 2017). "Additionally, our data provide evidence for the role played by Syndecan-1 in synchronously fine tuning multiple signaling pathways including IL-6/STAT3/gp130, inflammatory cytokines, Notch, and EGFR, implicated in breast cancer stemness." (PMID 28270211, 2017). "Furthermore, we found that GD3 colocalized and associated with EGFR, and it activated EGFR signaling in breast cancer cell lines and breast CSCs." (PMID 28537895, 2017). "Similarly, a study has shown a reduction of EGFR activation in EPA- or DHA-induced apoptosis in breast cancer (MDA-MB-231 and MCF-7) cells, associated to a reduction of Bcl2 and caspase-8 expression." (PMID 28869531, 2017).
breast carcinoma (continued). "However, higher expression of EGFR increased the risk of brain metastases in breast cancer patients." (PMID 28038448, 2017). "Overexpression of GFR signalling through EGFR or HER2 may also lead to activation of MAPK in ER+ breast cancer, causing loss of ERα expression." (PMID 27923036, 2017). "MMP17 has been implicated in breast cancer as a positive modifier of EGFR signalling." (PMID 28120820, 2017). "Our aim was to evaluate the association of the epidermal growth factor receptor gene (EGFR) polymorphism R497K (rs2227983) with prognostic features and clinical outcomes of breast cancer, including the pathological response to NAC and the recurrence-free survival (RFS)." (PMID 29267323, 2017). "Furthermore, we found that GD3 was associated with EGFR and activated EGFR signaling in both breast CSCs and breast cancer cell lines." (PMID 28537895, 2017). "Furthermore, it modified cell morphology, inducing cell-cell junctions, evoked EMT/MET reprogramming and suppressed the expression of major matrix effectors (matrix metalloproteinases and EGFR) implicated in breast cancer progression." (PMID 28332606, 2017). "Moreover, CD147 correlates with epidermal growth factor receptor activity in association with tumor chemoresistance in a cancer stem cell-like cell line derived from breast cancer cells." (PMID 27363028, 2016). "Next, to determine whether the delay in EGFR degradation is dependent on PTEN catalytic activity we carried out EGFR degradation assay in PTEN-deficient MDA-MB 468 breast cancer cells." (PMID 26869029, 2016). "An activation of EGFR signaling in MCF7 cells led to an increase of EMT-phenotypes, inhibited apoptotic events, and induced the loss of cytokeratin expression so that the analysis of EGFR could be an important prognostic and predictive marker in breast cancer." (PMID 27529216, 2016). "Our data suggest that upregulation of CD44v6 in acquired resistant breast cancer may contribute to a gain in the aggressive phenotype of these cells and loss of endocrine response through transactivation of the EGFR pathway." (PMID 27379207, 2016). "The differences between MCF10A and MCF10CA1a from the CNV and exome sequencing analysis identified in this study may be useful to guide future diagnostic efforts to understand EGFR inhibition sensitivity in breast cancer." (PMID 25969993, 2015). "As TKIs have been found to improve progression free survival (PFS) in NSCLC patients, determining the consequences of these EGFR mutations in breast cancer could be of benefit to shaping the management of disease." (PMID 25969993, 2015). "Due to the general importance of the EGFR-pathway in breast cancer biology, the identification of EGFR-mutations in breast cancer may aid further investigation as well as guide the use of EGFR inhibitors." (PMID 26267891, 2015). "Moreover, BRCA1-related breast cancer is associated with a basal-like phenotype in which EGFR is a basal marker and approximately one in five BRCA1 mutated breast cancers which were negative for ER and PR expressed AR." (PMID 25695063, 2015). "Therefore, the aim of the present study was to examine the presence of relevant somatic EGFR mutations in Norwegian breast cancer patients." (PMID 26267891, 2015). "Although EGFR is rarely mutated in breast cancers, the wild type protein is frequently overexpressed in breast tumors, and EGFR has been suggested to be a therapeutic target in triple-negative (Estrogen Receptor-, Progesterone Receptor-, and HER2-negative) breast cancers." (PMID 25865227, 2015). "Regarding the associations of HER family receptor mRNA expression with breast cancer subtypes, high EGFR mRNA expression was associated with triple-negative breast cancer (TNBC) (p < 0.001), while high HER2 mRNA expression with luminal-HER2 and HER2-enriched subtypes (both, p < 0.001)." (PMID 26021752, 2015).